MIR3926-2 (microRNA 3926-2)
Synonyms: hsa-mir-3926-2; mir-3926-2
Gene: MicroRNA gene on chromosome 8 (12,727,237 to 12,727,299, forward strand). Ensembl gene ENSG00000283523.
Homologues: Orthologues: macaque MIR3926-2 (100% identical).